EXOSC9 (exosome component 9)
Description:
Non-catalytic component of the RNA exosome complex which has 3'->5' exoribonuclease activity and participates in a multitude of cellular RNA processing and degradation events. In the nucleus, the RNA exosome complex is involved in proper maturation of stable RNA species such as rRNA, snRNA and snoRNA, in the elimination of RNA processing by-products and non-coding 'pervasive' transcripts, such as antisense RNA species and promoter-upstream transcripts (PROMPTs), and of mRNAs with processing defects, thereby limiting or excluding their export to the cytoplasm. The RNA exosome may be involved in Ig class switch recombination (CSR) and/or Ig variable region somatic hypermutation (SHM) by targeting AICDA deamination activity to transcribed dsDNA substrates. In the cytoplasm, the RNA exosome complex is involved in general mRNA turnover and specifically degrades inherently unstable mRNAs containing AU-rich elements (AREs) within their 3' untranslated regions, and in RNA surveillance pathways, preventing translation of aberrant mRNAs. It seems to be involved in degradation of histone mRNA. The catalytic inactive RNA exosome core complex of 9 subunits (Exo-9) is proposed to play a pivotal role in the binding and presentation of RNA for ribonucleolysis, and to serve as a scaffold for the association with catalytic subunits and accessory proteins or complexes. EXOSC9 binds to ARE-containing RNAs.
Synonyms: PM/Scl-75; PMSCL1; Rrp45p; RRP45; p5; p6; PCH1D
Tractability: Small molecule: a structure with a bound ligand is known. PROTAC: UniProt records ubiquitination sites on it; ubiquitination databases record sites on it; its protein half-life has been measured.
Gene: Protein-coding gene on chromosome 4 (121,801,318 to 121,817,021, forward strand). Ensembl gene ENSG00000123737.
Subcellular location: Cytoplasm; Nucleus; Nucleus, nucleolus; Nucleus, nucleoplasm; Nucleus, nucleolus (Isoform 1); Nucleus, nucleolus (Isoform 2); Nucleus (Isoform 3)
Subcellular location (Human Protein Atlas): Nucleoli; Nucleoplasm
Pathways (Reactome):
Metabolism of RNA: Butyrate Response Factor 1 (BRF1) binds and destabilizes mRNA; KSRP (KHSRP) binds and destabilizes mRNA; Major pathway of rRNA processing in the nucleolus and cytosol; Nuclear RNA decay; Tristetraprolin (TTP, ZFP36) binds and destabilizes mRNA; mRNA decay by 3' to 5' exoribonuclease
Cellular responses to stimuli: ATF4 activates genes in response to endoplasmic reticulum stress
Gene Ontology:
Molecular function: mRNA 3'-UTR AU-rich region binding; protein binding; RNA binding; RNA exonuclease activity; 3'-5'-RNA exonuclease activity; RNA polymerase II-specific DNA-binding transcription factor binding
Biological process: mRNA catabolic process; nuclear mRNA surveillance; nuclear polyadenylation-dependent rRNA catabolic process; nuclear-transcribed mRNA catabolic process; positive regulation of cell growth; RNA catabolic process; RNA processing; exonucleolytic trimming to generate mature 3'-end of 5.8S rRNA from tricistronic rRNA transcript (SSU-rRNA, 5.8S rRNA, LSU-rRNA); immune response; rRNA catabolic process; rRNA processing; TRAMP-dependent tRNA surveillance pathway; U1 snRNA 3'-end processing; U4 snRNA 3'-end processing; U5 snRNA 3'-end processing; positive regulation of transcription by RNA polymerase II
Cellular component: cytoplasm; cytosol; exosome (RNase complex); extracellular exosome; nuclear chromosome; nuclear exosome (RNase complex); nucleolus; nucleoplasm; nucleus; cytoplasmic exosome (RNase complex); nucleolar exosome (RNase complex); exoribonuclease complex
Genetic constraint (gnomAD): Loss-of-function variants: 25 observed, 31.16 expected, observed/expected ratio (o/e) 0.8, 90% interval 0.58 to 1.12. The upper end of that interval is the gene's LOEUF score, 1.12, which puts it in group 4 of 6, group 1 being the genes least tolerant of losing a copy. Missense variants: 349 observed, 345.98 expected, observed/expected ratio (o/e) 1.01, 90% interval 0.92 to 1.1. Synonymous variants: 113 observed, 115.14 expected, observed/expected ratio (o/e) 0.98, 90% interval 0.84 to 1.15.
Homologues: Orthologues: chimpanzee EXOSC9 (99% identical), macaque EXOSC9 (99% identical), guinea pig EXOSC9 (95% identical), rabbit EXOSC9 (94% identical), rat Exosc9 (93% identical), mouse Exosc9 (92% identical), dog EXOSC9 (92% identical), pig EXOSC9 (90% identical), tropical clawed frog exosc9 (70% identical), zebrafish exosc9 (64% identical), Caenorhabditis elegans exos-9 (31% identical), Drosophila melanogaster Rrp45 (28% identical). Paralogues in human: EXOSC7 (18% identical), EXOSC8 (17% identical).
Diseases named in the same sentence as EXOSC9 in open-access papers:
EXOSC9 is named in the same sentence as 19 diseases in open-access papers, as found by Europe PMC text mining. Sharing a sentence is not in itself a finding about the gene and the disease. The quoted sentences say what the papers report.
breast carcinoma (4 papers, 2020 to 2024). "Elevated Exosc9 is frequently observed and drives the growth of endocrine therapy-resistant (ET-R) HR+ breast cancer (BCa) cells." (PMID 37887339, 2023). "EXOSC9 depletion also affected the number of breast cancer MCF-7 and cervical cancer HeLa cells upon exposure to conditions of stress." (PMID 32518284, 2020). "To evaluate the function of EXOSC9 in stress resistance in cancer cells, we first established stable EXOSC9-depleted breast cancer MDA-MB-231 cells using shRNA-expressing lentiviral vectors." (PMID 32518284, 2020). "In addition, Exosc9 is one of the genes identified to support lung and breast cancer cell growth during hypoxia." (PMID 37887339, 2023). "The depletion of Exosc9 induces excess APOBEC3G mRNA expression and, subsequently, reduces P-body formation and stress resistance in breast cancer cells." (PMID 37887339, 2023). "A recent study reported that EXOSC4 knockdown resulted in the downregulation of other RNA exosome components, EXOSC3 and EXOSC9, at the protein level in MDA-MB-231 cells, a breast cancer cell line." (PMID 35008922, 2022).
Cerebellar atrophy (4 papers, 2018 to 2025). Cerebellar atrophy is defined as a cerebellum with initially normal structures, in a posterior fossa with normal size, which displays enlarged fissures (interfolial spaces) in comparison to the foliae secondary to loss of tissue. "Mutations in EXOSC9 can cause a Pontocerebellar Hypoplasia (PCH)-like disease with cerebellar atrophy and spinal motor neuron disease." (PMID 41463494, 2025). "EXOSC9 mutations are associated with PCH1d that exhibit spinal motor neuropathy and cerebellar atrophy, while the abnormalities of the pons are modest." (PMID 34948199, 2021). "In summary, we show that variants in EXOSC9 result in a neurological syndrome combining cerebellar atrophy and spinal motoneuronopathy, thus expanding the list of human exosomopathies." (PMID 29727687, 2018). "Based on the preliminary diagnosis of cerebral and cerebellar atrophy on brain MRI, only three genes causative of AR forms of white matter diseases were lying within the observed 24 Mb regions of homozygosity, including EXOSC9 (OMIM *606180), SPATA5 (OMIM *613940) and MFSD8 (OMIM *611124)." (PMID 36833170, 2023). "In summary, we have described four independent individuals who are affected by variants in EXOSC9 and who presented with motor axonopathy resembling SMA, cerebellar atrophy, and in one affected individual, multiple bone fractures." (PMID 29727687, 2018). "The involvement of spinal motor neurons together with cerebellar atrophy, with or without pontine involvement, is a common feature in affected individuals with variants in different exosomal subunit (EXOSC3, EXOSC8, and EXOSC9) and belongs to the spectrum of PCH1-related disorders." (PMID 29727687, 2018).
pontocerebellar hypoplasia (3 papers, 2020 to 2022). Pontocerebellar hypoplasias (PCH) are a rare heterogeneous group of diseases characterized by hypoplasia and atrophy and/or early neurodegeneration of the cerebellum and pons. "EXOSC9 is linked to the rare disorder pontocerebellar hypoplasia, the expression of CNOT6 is reported to be altered in several types of tumor cells, and it has been suggested that it plays a role in preventing cell death and senescence." (PMID 35159331, 2022). "Mutations in EXOSC3, EXOSC8, and EXOSC9 cause several forms of autosomal-recessive neurodegenerative disease, pontocerebellar hypoplasia (PCH), namely, PCH type 1b (PCH1b), PCH1c, and PCH1d, respectively." (PMID 34948199, 2021).
pontocerebellar hypoplasia type 1 (3 papers, 2020 to 2025). "Variants of exosome component 3 (EXOSC3), exosome component 8 (EXOSC8) and exosome component 9 (EXOSC9) have all been associated with pontocerebellar hypoplasia type 1 (PCH1B-D)." (PMID 40428407, 2025). "Namely, EXOSC9 dysfunction leads to a neurodegenerative disease pontocerebellar hypoplasia type 1b, and neurodegeneration occurs in most MPS types." (PMID 35456399, 2022).
Cerebellar hypoplasia (2 papers, 2018 to 2020). Cerebellar hypoplasia is a descriptive term implying a cerebellum with a reduced volume, but a normal shape and is stable over time. "A recent paper reported that human patients with mutations that decrease EXOSC9 expression show cerebellar hypoplasia similar to that observed with mutations in other RNA exosome components such as EXOSC3 and EXOSC8 genes." (PMID 32518284, 2020).
pancreatic adenocarcinoma (2 papers, 2020 to 2023). "Others report that high Exosc9 activity correlates with poor prognosis in adrenocortical, lung, and pancreatic adenocarcinoma." (PMID 37887339, 2023). "The low-EXOSC9 target signature, indicating high EXOSC9 activity, was significantly correlated with poor prognosis in adrenocortical carcinoma, lung adenocarcinoma, and pancreatic adenocarcinoma, among various cancers from the TCGA datasets." (PMID 32518284, 2020).
COVID-19 (1 paper, 2023). A disease caused by infection with severe acute respiratory syndrome coronavirus 2. "Like EXOSC2, higher expression levels of EXOSC7 and EXOSC9 are significantly associated with higher risk for clinical COVID-19 (P < 0.05)." (PMID 36241425, 2023).
Intellectual disability (1 paper, 2024). "For example, loss of EXOSC3 or EXOSC9 gene function has been associated with a neurodevelopmental syndrome that includes intellectual disability and axon degeneration during infancy." (PMID 39480871, 2024). "Moreover, mutations in EXOSC3 and EXOSC9 are also associated with intellectual disability in humans and mutations in EXOSC8 causes behavioral defects in zebrafish." (PMID 39480871, 2024).
pancreatic cancer (1 paper, 2022). "We found that knockdown of EXOSC10, but not EXOSC3 or EXOSC9, caused growth inhibition of pancreatic cancer cells." (PMID 35008922, 2022).
cancer (7 papers, 2016 to 2024). A tumor composed of atypical neoplastic, often pleomorphic cells that invade other tissues. "HPF1, RPL34, and EXOSC9 were the most common genes present in FRG1 associated pathways across the cancer types." (PMID 34795329, 2021). "EXOSC8 and EXOSC9 are associated with many diseases, but their role in cancer has recently been uncovered." (PMID 34795329, 2021). "Reduction in EXOSC9 was associated with reducing of p-body formation in cancer cells." (PMID 34795329, 2021). "In this study, we revealed that EXOSC9, a component of the 3′-5′ mRNA degradation machinery RNA exosome complex, promotes the formation of P-bodies, which is likely associated with the translational regulation of some mRNAs, stress resistance, and tumorigenicity in cancers." (PMID 32518284, 2020). "EXOSC9 and other RNA exosome components are involved in stress resistance and P-body formation in cancer cells." (PMID 32518284, 2020). "To address this, here, we examined cell growth under different stress conditions such as nutrient starvation, genotoxic stress, endoplasmic reticulum (ER) stress, and oxidative stress, as well as tumorigenicity, using EXOSC9-depleted cancer cells." (PMID 32518284, 2020). "Previously, we identified EXOSC9 as an essential gene for lung and cancer cell growth during hypoxia based on genome-wide shRNA library screening." (PMID 32518284, 2020). "In parallel, lower expression of the EXOSC9-target signature was also found to correlate with poor prognosis in some cancers among various cancers from the TCGA datasets." (PMID 32518284, 2020). "Database analyses further showed that higher EXOSC9 activity, estimated based on the expression of 343 target genes, was correlated with poorer prognosis in some cancer patients." (PMID 32518284, 2020). "Taken together, EXOSC9 is indispensable for the survival of cancer cells under various conditions of stress." (PMID 32518284, 2020). "Here, we examined the effects of EXOSC9 depletion on cancer cell growth under various stress conditions." (PMID 32518284, 2020). "Genes encoding exosome complex components are linked to pathologies including cancer (DIS3), immune disorders (EXOSC9 and EXOSC10) and congenital neurological disorders (EXOSC3 and EXOSC8)." (PMID 27543448, 2016). "Interestingly, compared to noncancerous mammary epithelial cells, Exosc9 protein expression is reduced in MCF7 cancer cells while Exosc9 protein expression is induced in tamoxifen-resistant (TamR-7) cells." (PMID 37887339, 2023). "In our model we found EXOSC9 to be highly correlated with FRG1 in multiple cancer types." (PMID 34795329, 2021). "EXOSC9 depletion attenuated growth and survival under various stress conditions in cancer cells." (PMID 32518284, 2020). "Since EMT promotes drug resistance in such cells, it might also partially contribute to the EXOSC9-mediated stress resistance in cancer cells observed in this study." (PMID 32518284, 2020). "In conclusion, we show that EXOSC9 depletion attenuates stress resistance and P-body formation in cancer cells and that higher EXOSC9 activity correlates with poor prognosis for patients with some types of cancers." (PMID 32518284, 2020). "Thus, we set 343 EXOSC9-target gene candidates including APOBEC3G in MDA-MB-231 cells as the “EXOSC9 target signature” and evaluated the correlation between this signature and cancer patient prognosis using the TCGA datasets." (PMID 32518284, 2020). "APOBEC3G mRNA regulation by EXOSC9 might also depend on the type of cancer." (PMID 32518284, 2020). "However, whether and how EXOSC9, a component of the RNA exosome complex, regulates adaptation to stress conditions and tumorigenicity in cancer cells remain unclear." (PMID 32518284, 2020). "Thus, drugs targeting activity of the RNA exosome complex or EXOSC9 might be useful for cancer treatment." (PMID 32518284, 2020).
cancer (continued). "Thus, drugs targeting the activity of the RNA exosome complex or EXOSC9 might also be useful for these cancers." (PMID 32518284, 2020). "However, whether and how EXOSC9 regulates adaptation to other stress conditions and tumorigenicity in cancer cells remain unclear." (PMID 32518284, 2020). "From the top 20 genes correlated with FRG1 across cancer types, we found that three genes (HPF1, RPL34, and EXOSC9) were common." (PMID 34795329, 2021). "Thus, high EXOSC9 activity might result in a worse prognosis for these cancers." (PMID 32518284, 2020).
tumor (3 papers, 2020 to 2025). "EXOSC9 is a core component of the RNA exosome, but the expression of only this marker is insufficient to estimate RNA exosome complex activity in tumor tissues." (PMID 32518284, 2020). "EXOSC9 depletion markedly attenuated MDA-MB-231 cell tumor growth in immunodeficient mice." (PMID 32518284, 2020). "Finally, EXOSC9 also promoted xenografted tumor growth of MDA-MB-231 cells in an intact RNA-binding motif-dependent manner." (PMID 32518284, 2020). "Thus, the role of EXOSC9 in tumor formation was evaluated using xenograft assays." (PMID 32518284, 2020). "Further, 25 days after inoculation, more apoptotic cells were detected in tumors formed by EXOSC9 KD MDA-MB-231 cells, compared to numbers in control tumors, which was concomitant with smaller tumor volumes." (PMID 32518284, 2020). "Moreover, the re-expression of WT EXOSC9, but not MUT EXOSC9, restored the tumor growth of EXOSC9-depleted MDA-MB-231 cells." (PMID 32518284, 2020).
EXOSC9 also shares sentences with these, for which no sentence is quoted: Myositis (2 papers); adrenocortical carcinoma (1); cervical cancer (1); colorectal cancer (1); genetic diseases (1); immune disorders (1); lung adenocarcinoma (1); neurodegenerative disease (1).